BMP4 (bone morphogenetic protein 4)
Description:
Growth factor of the TGF-beta superfamily that plays essential roles in many developmental processes, including neurogenesis, vascular development, angiogenesis and osteogenesis. Acts in concert with PTHLH/PTHRP to stimulate ductal outgrowth during embryonic mammary development and to inhibit hair follicle induction (By similarity). Initiates the canonical BMP signaling cascade by associating with type I receptor BMPR1A and type II receptor BMPR2. Once all three components are bound together in a complex at the cell surface, BMPR2 phosphorylates and activates BMPR1A. In turn, BMPR1A propagates signal by phosphorylating SMAD1/5/8 that travel to the nucleus and act as activators and repressors of transcription of target genes. Positively regulates the expression of odontogenic development regulator MSX1 via inducing the IPO7-mediated import of SMAD1 to the nucleus (By similarity). Required for MSX1-mediated mesenchymal molar tooth bud development beyond the bud stage, via promoting Wnt signaling (By similarity). Acts as a positive regulator of odontoblast differentiation during mesenchymal tooth germ formation, expression is repressed during the bell stage by MSX1-mediated inhibition of CTNNB1 signaling (By similarity). Able to induce its own expression in dental mesenchymal cells and also in the neighboring dental epithelial cells via an MSX1-mediated pathway (By similarity). Can also signal through non-canonical BMP pathways such as ERK/MAP kinase, PI3K/Akt, or SRC cascades. For example, induces SRC phosphorylation which, in turn, activates VEGFR2, leading to an angiogenic response.
Synonyms: BMP2B; BMP2B1; MCOPS6; OFC11; ZYME
Tractability: Small molecule: it belongs to a druggable protein family. Antibody: its Gene Ontology location is reachable by antibodies, with high confidence; UniProt places it where antibodies can reach, with medium confidence; UniProt predicts a signal peptide or a membrane-spanning region. PROTAC: ubiquitination databases record sites on it; a small molecule that binds it is known.
Target class: Enzyme; Metallo protease M12A subfamily; Metallo protease; Protease; Metallo protease MAM clan
Chemical probes: ML347
Gene: Protein-coding gene on chromosome 14 (53,949,736 to 53,958,761, reverse strand). Ensembl gene ENSG00000125378.
Subcellular location: Secreted, extracellular space, extracellular matrix
Pathways (Reactome):
Developmental Biology: Formation of intermediate mesoderm; Formation of lateral plate mesoderm; Formation of paraxial mesoderm; Formation of the nephric duct; Formation of the ureteric bud; Germ layer formation at gastrulation; Specification of the neural plate border
Metabolism of proteins: Post-translational protein phosphorylation; Regulation of Insulin-like Growth Factor (IGF) transport and uptake by Insulin-like Growth Factor Binding Proteins (IGFBPs)
Extracellular matrix organization: Molecules associated with elastic fibres
Reproduction: Specification of primordial germ cells
Gene Ontology:
Molecular function: BMP receptor binding; chemoattractant activity; co-receptor binding; cytokine activity; protein binding; growth factor activity; heparin binding
Biological process: blood vessel endothelial cell proliferation involved in sprouting angiogenesis; BMP signaling pathway; branching involved in ureteric bud morphogenesis; bronchus development; bud dilation involved in lung branching; cellular response to BMP stimulus; epithelial cell proliferation involved in lung morphogenesis; epithelial tube branching involved in lung morphogenesis; heart induction; heart morphogenesis; hematopoietic progenitor cell differentiation; intermediate mesodermal cell differentiation; kidney development; lung alveolus development; lung morphogenesis; lung vasculature development; lymphoid progenitor cell differentiation; macrophage differentiation; mesoderm development; mesonephros development; monocyte differentiation; negative regulation of branching involved in ureteric bud morphogenesis; negative regulation of cell cycle; negative regulation of cell population proliferation; negative regulation of DNA-templated transcription; and 92 more
Cellular component: extracellular region; endoplasmic reticulum lumen
Genetic constraint (gnomAD): Loss-of-function variants: 3 observed, 30.08 expected, observed/expected ratio (o/e) 0.0997, 90% interval 0.044 to 0.26. The upper end of that interval is the gene's LOEUF score, 0.26, which puts it in group 1 of 6, group 1 being the genes least tolerant of losing a copy. Missense variants: 455 observed, 569.57 expected, observed/expected ratio (o/e) 0.8, 90% interval 0.74 to 0.86. Synonymous variants: 197 observed, 221.98 expected, observed/expected ratio (o/e) 0.89, 90% interval 0.79 to 1.
Gene-disease validity (ClinGen):
ClinGen rates the evidence that BMP4 causes each of these diseases.
BMP4-related ocular growth disorder (autosomal dominant): Definitive. Any ocular growth disorder in which the cause of the disease is a mutation in the BMP4 gene.
Homologues: Orthologues: chimpanzee BMP4 (99% identical), macaque BMP4 (99% identical), pig BMP4 (99% identical), dog BMP4 (98% identical), mouse Bmp4 (97% identical), rat Bmp4 (97% identical), rabbit BMP4 (97% identical), guinea pig BMP4 (92% identical), tropical clawed frog bmp4 (82% identical), zebrafish bmp4 (70% identical). Paralogues in human: BMP2 (61% identical), BMP6 (30% identical), GDF2 (30% identical), BMP10 (30% identical), BMP7 (29% identical), BMP5 (29% identical), GDF6 (28% identical), GDF7 (27% identical), BMP8A (27% identical), BMP8B (27% identical), GDF5 (26% identical), GDF3 (24% identical), and 19 more.
Diseases named in the same sentence as BMP4 in open-access papers:
BMP4 is named in the same sentence as 393 diseases in open-access papers, as found by Europe PMC text mining. Sharing a sentence is not in itself a finding about the gene and the disease. The quoted sentences say what the papers report.
breast carcinoma (93 papers, 2007 to 2026). "While SMAD4 is normally expressed in breast cancer where we have shown that BMP4 has anti-metastatic activity, in colorectal and pancreatic cancers where a pro-tumor role of BMP4 is observed, SMAD4 is mutated or lost in up to 40% of cases." (PMID 38689334, 2024). "Similar to normal stem cells, BMP4 has been associated with CSCs in several tumors including breast cancers and glioblastoma." (PMID 35565225, 2022). "High BMP-4 expression levels are found in 25% of breast cancer patients and are associated with a high risk of tumor recurrence." (PMID 31409851, 2019). "We have previously shown that the growth inhibition caused by BMP4 in breast cancer cell lines growing in monolayer culture is due to a G1 cell cycle arrest." (PMID 24053318, 2013). "BMP4 is implicated in promoting metastasis in breast cancer by enhancing cancer stemness." (PMID 38786043, 2024). "ER-α is thought to be indispensable for this effect on the BMP-4 promoter and may be part of the mechanism of this agents in reducing both osteoporosis and breast cancer risk." (PMID 28733469, 2017). "Likewise, a variant in BMP4 has been found to be associated with colorectal cancer; also a variant in 2q35 has been found to be associated with breast cancer." (PMID 23704328, 2013). "In breast cancer, bone morphogenetic protein 4 (BMP‐4) activates the Notch pathway in a Smad4‐dependent manner, promoting stemness and EMT programs." (PMID 40665579, 2025). "Conversely, in patients affected by luminal B breast carcinomas only a high level of BMP-4 and SDF-1 positively correlated with a better overall survival (BMP-4 p = 0.0045; SDF-1 p = 0.012)." (PMID 39859358, 2025). "In a cohort of breast cancer patients for whom outcome and therapy data were available, patients whose tumours had low levels of BMP4 protein demonstrated a reduced rate of relapse if on statin therapy." (PMID 39273106, 2024). "In previous studies, we have reported that BMP4 potently suppresses metastasis in preclinical mouse models where breast cancer cells retained SMAD4 activity to transduce canonical signalling." (PMID 38689334, 2024). "We reported previously that in preclinical models, BMP4 is a potent inhibitor of breast cancer metastasis and that high BMP4 protein levels predict favourable patient outcomes." (PMID 39273106, 2024). "To identify therapeutically targetable pathways regulated by BMP4 to suppress metastatic disease, we interrogated a previously generated RNA sequencing dataset derived from breast cancer cells isolated from primary xenograft tumours." (PMID 39273106, 2024). "Analysis of a cohort of primary breast cancers revealed a reduced relapse rate for patients on statin therapy if their tumours exhibited low BMP4 levels." (PMID 39273106, 2024). "We and others have shown that bone morphogenetic protein 4 (BMP4) is a potent inhibitor of breast cancer metastasis, although other studies report contradictory findings for the role of BMP4." (PMID 39273106, 2024). "We have reported a robust anti-metastatic effect of BMP4 signalling in pre-clinical models of breast cancer and highlighted the potential of activating BMP4 signalling as a viable therapeutic approach to treat metastatic breast cancer." (PMID 38689334, 2024). "We examined the effect of statin usage on breast cancer relapse in a cohort of 407 breast cancer patients for which we had previously revealed the prevalence of BMP4 at the protein level." (PMID 39273106, 2024). "In breast cancer, Bone Morphogenetic Protein 4 (BMP-4) enhances stemness and EMT programs by activating the Notch pathway in a Smad4-dependent manner." (PMID 39456967, 2024). "Reduced expression of BMP4 supressed osteoclastic cell differentiation with regulation of Fam20C in breast cancer." (PMID 37333824, 2023).
breast carcinoma (continued). "Most of these genes were associated with cancers of metabolic systems (DUSP6, SGK1, BMP4, RASGRF1, GDF15) followed by breast cancer (CACNA2D3, ITGB7), cancers of the central nervous system (PRKCA), or leukemia (MECOM, JAK3)." (PMID 36624125, 2023). "Conversely, poor breast cancer patients’ outcomes in the context of short distant-metastasis–free survival (DMFS), OS, and RFS were associated with low BMP4 expression levels using a multivariate analysis." (PMID 36510219, 2022). "In particular, BMP-4 enhances epithelial mesenchymal transition (EMT) in breast carcinoma cell lines." (PMID 35150338, 2022). "Studies have shown that cytokine sensitivity screening considers the BMP4 signaling pathway to be crucial for treating ER + breast cancer." (PMID 35669516, 2022). "For instance, in breast cancer, BMP4 promotes tumorigenesis, while another study showed, paradoxically, a tumor-suppressing function of BMP4." (PMID 35565225, 2022). "Several BMPs, including BMP2, BMP6, BMP9, BMP10, BMP15, and GDF9a inhibit the proliferation of breast cancer cells, whereas BMP4 and BMP7 can either promote or inhibit proliferation in different contexts." (PMID 35846378, 2022). "For example, it is known that BMP4 can exert pro-tumourigenic functions in breast cancer, where it mediates migration and invasion, which can be blocked via CHRDL1, whereas CHRDL1 induces the neuronal differentiation of neural stem cells." (PMID 36497175, 2022). "It has been demonstrated that both endogenous CHRDL1 and recombinant CHRDL1 suppress the migration and invasion induced by BMP4 signaling in different breast cancer cell lines." (PMID 35494000, 2022). "BMP-4 reduces the secretion of granulocyte colony-stimulating factor (G-CSF) from mammary tumors, which is likely a critical factor for the expansion of myeloid-derived suppressor cells (MDSCs) and progression of metastasis." (PMID 35693928, 2022). "For this, we performed bioinformatics analysis using GOBO49 and TCGA-BRCA50 online databases to identify any correlation between BMP4 gene expression and breast cancer clinical features." (PMID 33649296, 2021). "Chordin-like 1(CHRDL1), as a secreted antagonist of BMP signaling, has been previously reported to predominantly suppress BMP4-induced migration and invasion, and its higher expression indicates better clinical outcomes in breast cancer." (PMID 34745928, 2021). "Analysis of the TCGA-BRCA dataset revealed a similar pattern, indicating that the lowest BMP4 expression levels correlate with the most aggressive breast cancer subtypes." (PMID 33649296, 2021). "In breast cancer BMP-4 promotes the migration and invasion of cancer cells, at least in part by up-regulating the expressions of matrix metalloproteinase-1 and chemokine receptor type 4." (PMID 34501309, 2021). "Chordin-like 1 is a negative regulator of bone morphogenetic protein 4-induced migration and invasion in breast cancer." (PMID 33585078, 2021). "BMP4 has emerged in many cancers, including breast cancer, prostate cancer, colorectal cancer and non–small‐cell lung cancer." (PMID 33452764, 2021). "It was reported that BMP4 possesses both tumor-suppressive and oncogenic properties in breast cancer and that it is a potent suppressor of breast cancer metastasis." (PMID 32093026, 2020). "In breast cancer cells, overexpressing ci-miRNA-191, was associated with upregulated levels of TGF-β pathway genes (TGFβ2, SMAD3, BMP4, JUN, FOS, PTGS2, CTGF, and VEGFA), thus promoting breast cancer growth and metastasis." (PMID 32942528, 2020). "BMP-4 has also been shown to be necessary for the invasion of breast cancer cells, both in vivo and in vitro." (PMID 31409851, 2019). "Using web-based databases we analyzed mRNA expression levels of GREM1 and BMP4 in breast cancer cell lines and a breast cancer patient cohort (TCGA) and found that these two genes are also co-expressed in some tumor cell lines and primary tumors." (PMID 31694641, 2019).
breast carcinoma (continued). "To characterise the BMP4 responses, we predominantly used the human breast cancer cell line MDA-MB-231 and the mouse fibroblast cell line NIH-3T3, both of which induce robust SMAD1/5 phosphorylation in response to BMP4." (PMID 31217285, 2019). "In this study, our results suggest that Notch signaling is necessary for the BMP-4-mediated EMT of breast cancer cells." (PMID 31409851, 2019). "We further analyzed the relevance of BMP4 or SMAD1 mRNA levels in primary breast cancer with bone-specific metastasis based on the GSE2034_GSE2603 data set." (PMID 31222004, 2019). "The expression levels of Jagged-1 and BMP-4 were higher than the baseline level (as the average level measured in paired normal tissue) in approximately 18% and 26% of breast cancer tissue samples, respectively." (PMID 31409851, 2019). "This highlighted BMP4 and its downstream pathway activation as a therapeutic opportunity in ER+ breast cancer." (PMID 31860871, 2019). "BMP-4 also activated the Notch signaling pathway which is critical for TGF-β-mediated EMT in breast cancer cells and mouse mammary gland epithelial cells." (PMID 31409851, 2019). "BMP2, reported to promote invasion and progression of MCF-7 breast cancer cells, was substantially elevated in all three metastatic lines, whereas the breast cancer metastasis suppressor gene BMP4 was suppressed in each of the three variants." (PMID 29720474, 2018). "TGF-β1 can induce the expression of miR-23a in breast cancer cells, HCC, and lung cancer cells, whereas BMP4 can induce the expression of miR-23a in breast cancer cells." (PMID 30577536, 2018). "Here we set out to uncover the transcriptional responses of breast cancer cell lines with different phenotypes by using one cell line that responds to BMP4 by reduced proliferation (T-47D) and another that reacts with increased migration (MDA-MB-231)." (PMID 28077088, 2017). "By combining genome-wide computational analyses and experimental data with functional validation, we were able to extend our knowledge about BMP4 signaling in breast cancer." (PMID 28077088, 2017). "We have previously searched for BMP4 target genes in a set of breast cancer cell lines that predominantly respond to BMP4 treatment by reduction of proliferation." (PMID 28077088, 2017). "We have previously characterized transcriptional responses of breast cancer cell lines to BMP4 by using microarray technology." (PMID 28077088, 2017). "Concordantly, data from breast cancer patient samples point to a correlation between elevated BMP4 levels and reduced proliferation as well as an increased risk of recurrence." (PMID 28077088, 2017). "BMP-4 is considered as an inhibitor of breast cancer cell growth, but can also have a synergistic effect on proliferation of breast cancer cells induced by fibroblast growth factor (FGF), EGF and HGF." (PMID 28733469, 2017). "We and others have shown that BMP4 reduces the proliferation of breast cancer cell lines, while simultaneously inducing migration and invasion in a subset of cell lines." (PMID 28077088, 2017). "Integrating RNA-seq and DNase-seq data showed that the phenotypic responses to BMP4 in breast cancer cell lines are reflected in transcriptomic and chromatin levels." (PMID 28077088, 2017). "Bone morphogenetic protein 2 (BMP2) and BMP4 are key regulators of the fate and differentiation of human mammary epithelial stem cells (SCs), as well as of their niches, and are involved in breast cancer development." (PMID 27740625, 2017). "BMP-4 increased MMP-3 and IL-6 in conditioned medium from treated mammary fibroblasts, suggesting BMP-4 can influence the tumour microenvironment to promote breast cancer invasion." (PMID 28733469, 2017). "Being able to uncover the mechanisms of these two different responses is essential for the understanding of the role of BMP4 in breast cancer pathogenesis." (PMID 28077088, 2017).